CDK5 (cyclin dependent kinase 5)
Diseases named in the same sentence as CDK5 in open-access papers (continued):
Sharing a sentence is not in itself a finding about the gene and the disease.
lung cancer (continued). "CDK5 signaling can be activated by EBV infection and viral EBNA-2 expression in lung cancer via upregulation of the CDK5 activator p35." (PMID 31159203, 2019). "Et al.’s study on CDK5 and lung cancer revealed a similar CDK5 proliferation and apoptosis trend in lung cancer cell lines when CDK5 activity was suppressed by siRNA." (PMID 29312535, 2017). "In lung cancer, we also discovered close correlations between CDK5 and pathological grading (r = 0.310, P < 0.001), TNM stage (r = 0.155, P = 0.003), and lymph node metastasis (r = 0.279, P < 0.001) by using Spearman analysis." (PMID 26860827, 2016). "Higher expression of CDK5 was found in lung cancer patients with lymphatic metastasis (76.6 %, 98/128) compared to those without lymphatic metastasis (37.6 %, 88/234, P < 0.001)." (PMID 26860827, 2016). "Nevertheless, further plans are needed to explore the potential function of CDK5 in vitro and in vivo in the carcinogenesis of and progression in lung cancer." (PMID 26860827, 2016). "Significantly increased expression of CDK5 in lung cancer tissues (51.5 %, 188/365) was found as compared to that in normal lung tissues (20 %, 6/30, P = 0.001)." (PMID 26860827, 2016). "The present study was aimed at exploring expression and clinicopathological significance of CDK5 in lung cancer." (PMID 26860827, 2016). "In the present study, immunohistochemistry on lung tissue microarrays was performed to explore the expression of CDK5 in lung cancer and normal lung tissues." (PMID 26860827, 2016). "We demonstrated that CDK5 was highly expressed in lung cancer, including non-small cell lung cancer and small cell lung cancer, compared to normal lung tissue." (PMID 26860827, 2016). "In lung cancer, high CDK5 expression predicts poor prognosis." (PMID 39800748, 2025). "Furthermore, LIMK1/CDK5 also increased the phosphorylation of β‐catenin in both gastric cancer and lung cancer cells." (PMID 40476449, 2025). "High expression of LIMK1 and CDK5 is associated with poor prognosis of ESCC patients, and the clinical and functional significance of LIMK1/CDK5‐Wnt/β‐catenin axis is also verified in esophageal adenocarcinoma, gastric cancer, and lung cancer." (PMID 40476449, 2025). "Additionally, we explored the clinical and functional significance of the LIMK1/CDK5‐Wnt/β‐catenin axis in esophageal adenocarcinoma, gastric cancer, and lung cancer." (PMID 40476449, 2025). "We found that the combined inhibition of ERK5 and CDK5 synergistically suppressed FAK function, decreased proliferation and caused DNA damage, which resulted in cell death in human cancer cell lines and mouse models of lung cancer." (PMID 39271958, 2024). "CDK5 positivity in lung cancer samples highly exceeded that in normal lung tissue (51.5% vs. 20%)." (PMID 39123371, 2024). "As DLC1 is often downregulated in lung cancer, CDK5-mediated DLC1 activation may have a limited impact." (PMID 37993880, 2023). "Several downstream targets of CDK5 have been identified in lung cancer." (PMID 37993880, 2023). "TTN-AS1 enhances the metastasis of lung cancer via regulating the miR-142-5p/CDK5 axis." (PMID 33614501, 2020). "We next determined whether TC2N induces Cdk5 degradation by promoting its ubiquitination in lung cancer cells." (PMID 30254375, 2019). "However, the clinicopathological impact and function of CDK5 in lung cancer remain poorly understood." (PMID 26860827, 2016).
lung cancer (continued). "Though expression of CDK5 was detected in lung cancer tissue and regulative mechanism of CDK5 was investigated in other cancers, the mechanism and exact role of CDK5 in the carcinogenesis and development of lung cancer remain unclear." (PMID 26860827, 2016). "As one of the downstream components of the EGFR-family-signaling pathway, the gene of CDK5 was amplified in lung cancer and it might be the common mechanism of oncogene activation in carcinogenesis." (PMID 26860827, 2016). "Our study, with a bigger sample size, approximately four times, confirmed that increased expression of CDK5 could be detected in lung cancer tissue compared with normal lung tissue and further supported that CDK5 was considered as an oncogene in lung cancer." (PMID 26860827, 2016). "So far, several articles have studied the potential role of CDK5 in lung cancer in vitro." (PMID 26860827, 2016). "Hence, the objective of this study was to explore the expression and clinicopathological significance of CDK5 in lung cancers and investigate its potential role of CDK5 as a biomarker for diagnosis and prognosis prediction for lung cancer patients." (PMID 26860827, 2016). "Several studies have demonstrated that CDK5 and its specific activator protein p35 were important for spontaneous metastasis and CDK5/p35 may represent a biomarker for prognosis in patients with prostate and lung cancer." (PMID 26146988, 2015). "The mechanism may support that CDK5 was closed related to lymphatic metastasis in lung cancer." (PMID 26860827, 2016). "Taken together, CDK5 might be a potential biomarker of lung cancer despite its histology types." (PMID 26860827, 2016). "The studies above of CDK5 in lung cancer suggested CDK5 may play an oncogenic role in lung cancer." (PMID 26860827, 2016). "For example, along with sumoylation, PPARγ phosphorylation could play an important role in lung cancer pathogenesis as fibroblast growth factor (FGF) activated- or cyclin-dependent kinase 5 (CDK5) phosphorylation of PPARγ revealed pathologically or physiologically altered PPARγ signaling." (PMID 26244663, 2015). "The Boyden chamber assay showed that LIMK1/CDK5 significantly promoted the invasion of EAC, gastric cancer, and lung cancer cells in a phosphorylation‐dependent manner." (PMID 40476449, 2025). "In this study, combination therapy with LIMK1 and CDK5 inhibitors exhibited a significant therapeutic effect on ESCC metastasis in a preclinical setting, as well as in EAC, gastric cancer, and lung cancer metastasis." (PMID 40476449, 2025). "Here, we found that in KRAS-driven lung cancer, FAK activation is synergistically controlled by ERK5 and CDK5." (PMID 39271958, 2024). "Furthermore, combination of ERK5 and CDK5 inhibition with XMD8-92 and Seliciclib, synergize in suppressing FAK and are expected to prevent feedback signaling leading to drug resistance, providing an additional treatment option for lung cancer patients with KRAS mutations." (PMID 39271958, 2024). "Thus, CDK5 might be used for the prediction to prognosis of lung cancer." (PMID 26860827, 2016). "Immunoblot in A549 lung cancer cells evidenced that concurrent inhibition of ERK5 and CDK5 cooperated in suppressing FAK activity as evidenced by the decreased phosphorylation of both FAKS910 and FAKS732 as well as FAKTyr397, which is essential for FAK full activation." (PMID 39271958, 2024). "In lung cancer, ASH1L also stimulates migration of cancer cells through Cdk5/p35 pathway." (PMID 34215297, 2021). "Besides, high expression of CDK5 suggests a poor prognosis for CRC, lung cancer, and liver cancer along with short overall survival in lung cancer and ovarian cancer." (PMID 33396266, 2020).
lung cancer (continued). "There was prominently higher expression of CDK5 in lung cancer, independent of various pathological subtypes, than in normal lung tissue." (PMID 26860827, 2016). "Patients with lung cancer expressing CDK5/p35 have a poorer prognosis than those that do not express." (PMID 25625291, 2015). "In addition, the inhibition of cyclin-dependent kinase 5 (CDK5) expression in the Lewis lung cancer cells of mice did not affect cell proliferation." (PMID 38782996, 2024). "PD-L1-enhancing oncogenes, such as EGFR, ALK, MET, AKT, MYC, and CDK5, were not identified as hits in this study because KRAS mutations in lung cancer cell lines (H2009 and H460) could establish distinct PD-L1 regulatory axes." (PMID 36357569, 2022).
tauopathy (31 papers, 2011 to 2025). Neurodegenerative disorders involving deposition of abnormal tau protein isoforms (tau proteins) in neurons and glial cells in the brain. "This receptor shift leads to dysregulated calcium influx and activation of Tau-related kinases such as GSK-3β and CDK5, which drive pathological phosphorylation at sites including Ser202/Thr205 and Ser396, commonly implicated in tauopathies." (PMID 40806766, 2025). "We then went on to study potential effects of APPsα on CDK5, as another major Tau kinase implicated in AD and other tauopathies." (PMID 36779015, 2023). "Neurodegenerative diseases are linked to tauopathy as a result of cyclin dependent kinase 5 (cdk5) binding to its p25 activator instead of its p35 activator and becoming over-activated." (PMID 27077074, 2016). "CDK5 activity and its effect on tauopathy can be associated with the modulation of its activator p35 and p25 cleaved form." (PMID 25309427, 2014). "In addition, calpain catalyzes the p35→p25 event that activates cyclin-dependent kinase 5 (cdk5), a proline-dependent kinase implicated in tau hyperphosphorylation in AD and other tauopathies." (PMID 21858230, 2011). "A similar reduction in tau phosphorylation was observed in a tauopathy model using 3xTg mice, confirming that CDK5 plays a key factor in AD pathology by phosphorylating tau at sites recognized by AT8." (PMID 39683582, 2024). "Network analysis shows that pioglitazone potentially targets two tauopathy-related proteins (GSK3β and CDK5) in AD." (PMID 35012639, 2022). "In conclusion, our in vivo and in vitro data directly implicate the 5LO enzymatic pathway as a key regulator of neuropathology and the tauopathy behavioral phenotype in a mouse model of pure tauopathy, the P301S line, via a cdk5 pathway‐dependent mechanism." (PMID 29106033, 2018). "Together with phosphatases, the synergistic role of CDK5 and GSK3β appears to be essential for tauopathy, and decreased CDK5 inhibits GSK3β function, which affects the disappearance of tauopathy." (PMID 25225483, 2014). "Pharmacological inhibition and genetic knock down of CDK5 have been reported as therapeutic approaches to the tauopathies, but the importance of this kinase and its role in neurons requires further study." (PMID 25309427, 2014). "3xTgAD and transgenic p25 mice treated with diaminothiazoles can reduce tauopathy and improve cognitive function by both CDK5 and GSK3β inhibition." (PMID 25309427, 2014). "Since both protein kinases are dysregulated in several neurodegenerative diseases (e.g., tauopathies) and in neuropathic pain, the investigated extract could show therapeutic effects in such disorders through dual inhibition of CDK5 and GSK-3β." (PMID 38732407, 2024). "In these animals we examined short-term memory and the expression of genes involved in the development of tauopathy (Htr7 and Cdk5), as well as biomarkers of neurodegenerative processes – the Bdnf gene and its receptors TrkB (the Ntrk2 gene) and p75NTR (the Ngfr gene)." (PMID 39027123, 2024). "The GSK-3β and CDK-5 pathways are intricately linked to Aβ aggregation, leading to tau hyperphosphorylation through the increased activity of both GSK-3β and CDK-5, ultimately resulting in Aβ-induced tauopathy." (PMID 39061930, 2024). "In validating the role of p25/Cdk5 in tauopathy, the authors derived iPSCs from frontotemporal dementia patient with Tau P301L mutation, generated P301L:Deltap35KI isogenic iPSC lines using CRISPR/Cas9 genome editing, and further created cerebral organoids from the isogenic iPSCs." (PMID 29937727, 2018). "Interestingly, p25/CDK5 inhibition has been reported to attenuate tauopathy in a model of frontotemporal dementia." (PMID 30425189, 2018).
tauopathy (continued). "However, in tauopathies such as AD, as well as in hibernation, tau undergoes hyperphosphorylation catalyzed by various protein kinases, including but not limited to glycogen GSK3β, cyclin-dependent kinase 5 (CDK5), and protein kinase A (PKA), accumulating an excess of 7-10 phosphate groups." (PMID 39128995, 2025). "Known tau kinases with well-documented roles in tauopathy were also predicted to have differential activity, including GSK3B, CDK5, and CDK5R1." (PMID 38895329, 2024). "Here, we examined the potential of APPsα to regulate two major Tau kinases, GSK3β and CDK5 in THY-Tau22 mice, a widely used mouse model of tauopathy." (PMID 36779015, 2023). "PPP2R5D is an interesting finding because its mutations can promote intellectual disability and the development of spatially restricted tauopathy by deregulating CDK5 and GSK3-beta in mice lacking PPP2R5D subunits." (PMID 35110995, 2021). "Epilepsy has been hypothesized as a tauopathy due to increased levels of P-tau which has been reported to be the result of increased GSK-3β and cdk5 activities." (PMID 30915013, 2019). "Among protein kinases, GSK-3β (a proline-directed protein kinases) and CDK5 (a non-PDPK non-proline-directed protein kinase) are probably the two most important kinases in tauopathy." (PMID 30333786, 2018). "This implies that structure-based drug design to development specifically target the CDK5 pathway may be beneficial to treat tauopathies without disrupting physiological Gs protein-mediated cellular responses." (PMID 38641599, 2024). "In contrast, unlike GSK-3β and CDK5, a series of protein phosphatases (PP-2A, PP-2B, and PP-1) can dephosphorylate protein tau in vitro and in vivo, which may act to protect against tauopathy." (PMID 30333786, 2018).
diabetes (29 papers, 2008 to 2025). "Recent reports strengthen the link between Cdk5 hyperactivation and diabetes-associated neurodegeneration." (PMID 34814918, 2021). "The early increase in p35 regulated Cdk5 is likely to underlie early phosphorylation of specific neurofilament side arm fragments, as indicated by the decreasing expression of Cdk5 with duration of diabetes paralleling decreasing phosphorylation of NF-M." (PMID 19834568, 2009). "Partial agonists may have more positive effects as PPARγ ligands in diabetes by decreasing adverse effects caused by the activation of unwanted transcription, favored by the binding of full agonists, and by preventing Cdk5-mediated PPARγ phosphorylation, improving insulin sensitivity." (PMID 37746194, 2022). "Furthermore, diabetes-associated hyperglycemia increased the CDK5 levels." (PMID 35874807, 2022). "mtDNA variants linking diabetes studied mostly in CRIF1 Deficiency in Mice, Cdk5 Expression in Diabetic Nephropathy, ALDH2*2 Mutant Mice, Mitochondrial Cardiomyopathy in Mice." (PMID 39835172, 2025). "In this study, we found that TFP5, a specific inhibitor of CDK5, efficiently protected the kidney function from the damage of diabetes." (PMID 35874807, 2022). "• Inhibition of adipocyte differentiation. • Increase of inflammatory molecules like COX2 and PEG2. • Induction of IL6 synthesis by adipocytes. • CDK5-dependent phosphorylation of PPARγ in adipocytes, favoring gene expression related to diabetes." (PMID 35422689, 2022). "The emerging evidence implicating CDK5 in several pathological processes, such as neurodegeneration, diabetes and cancer, points to CDK5 as an attractive therapeutic target." (PMID 31910742, 2020). "For instance, Cdk5 signaling is reported to be dysregulated in both diabetes and AD patients and Cdk5 hyper-activation is also sufficient to lead to the pathogenesis of diabetes." (PMID 32670025, 2020). "CDKAL1 was revealed to be an inhibitor of CDK5 to suppress the β-cell differentiation and further highlighted its importance in diabetes." (PMID 31098383, 2019). "Cdk5r1, due to its key role as a CDK regulator and the activity of the CDK5 complex in diabetes, was chosen as a potential candidate for further studies." (PMID 26788519, 2016). "Consistently, here we found that the FDA approved anti-diabetes drug pioglitazone can inhibit Cdk5 activity in both hippocampal neurons and APP/PS1 mutant mouse hippocampi." (PMID 25875370, 2015). "Previously it is reported that the anti-diabetes drug, troglitazone/pioglitazone can inhibit Cdk5 activity and the phosphorylation of its substrate tau in both SH-SY5Y cells and primary cultured cortical neurons." (PMID 25875370, 2015). "Here, our exciting results suggest that the FDA approved anti-diabetes drug pioglitazone can be a promising drug to prevent AD progression by decreasing p35 protein level and suppressing Cdk5 activity." (PMID 25875370, 2015). "Accordingly, ligands with high inhibitory effects on PPARγ phosphorylation by CDK5 that lack classical agonism are optimal drug candidates for diabetes." (PMID 26183621, 2015). "More interestingly, our results show that the FDA approved anti-diabetes drug pioglitazone can inhibit Cdk5 activity by decreasing p35 protein level in a proteasome dependent manner." (PMID 25875370, 2015). "This raises the possibility that Cdk5 can serve as a therapeutic target for both neurodegenerative disorders such as AD and diabetes." (PMID 24039692, 2013). "Cdk5 has also been reported to be an endogenous inhibitor of β cell differentiation, and its inhibition promotes β cell differentiation from ductal progenitor cells, further emphasising its importance in diabetes." (PMID 41181709, 2025). "Diabetes induces brain damage by regulating Cdk5 phosphorylation." (PMID 35966199, 2022). "The overactivation of CDK5 induced by HG is tightly responsible for podocyte injury in diabetes." (PMID 36213244, 2022).